CXCR2 (C-X-C motif chemokine receptor 2)
Diseases named in the same sentence as CXCR2 in open-access papers (continued):
Sharing a sentence is not in itself a finding about the gene and the disease.
tumor (continued). "More intriguingly, treatment of mice with SB225002 inhibited CXCR2 signaling in both microglia/macrophages and tumor cells." (PMID 34108959, 2021). "These facts indicated that CXCR2-mediated signaling was involved in tumor burden, showing immune cell infiltration in the tumor microenvironment." (PMID 34638514, 2021). "CXCR2, is a potent pro-tumorigenic chemokine receptor that can induce inflammation in the tumor microenvironment by mediating the recruitment of different stromal cells and thus promoting the progression of cancer cells." (PMID 34012923, 2021). "In patients with pancreatic adenocarcinoma, blockade of CCR2 prevented the accumulation of TAM in tumour sites but led to a compensatory CXCR2+ TANs influx, which possibly limited the intended treatment efficacy." (PMID 34464477, 2021). "The tumor microenvironment (TME) is regulated by chemokines and their G protein coupled receptors binds several ligands, including Cxcl5 which binds Cxcr2, to augment the pro-tumor immune response, tumor growth and metastasis." (PMID 33946495, 2021). "Another therapeutic approach involves the transduction of CXCR2 to antitumor lymphocytes which accumulate in the tumor niche and exhibit anticancer activity there." (PMID 33467722, 2021). "Combined treatment with a CSF1R inhibitor and a CXCR2 antagonist led to a significant reduction in tumor growth that was further enhanced by the addition of anti-PD1." (PMID 34944914, 2021). "CXCR2 has been shown to play a major role in tumor progression by recruiting polymorphonuclear type MDSCs and TANs into the tumor microenvironment in murine models of cancers such as colon cancer, pancreatic cancer, head and neck cancer, and melanoma." (PMID 34885241, 2021). "To further investigate the mechanisms involved in CXCR2 inhibitor-induced anti-tumor effects, we analyzed the neutrophils infiltration into tumor microenvironment." (PMID 33814009, 2021). "Increased expression of CXCL8 and its receptor, CXCR2, has been correlated with tumor progression after esophagectomy." (PMID 34640631, 2021). "Tumor bearing RET transgenic mice were treated with the CXCR2 inhibitor SB265610, which led to a significant survival benefit as compared to mice treated with the DMSO solution (control group)." (PMID 33578808, 2021). "The regulatory functions of CXCR2 in ovarian carcinogenesis and tumor immunity will be investigated in in vitro and in vivo experiments." (PMID 34840630, 2021). "While 91.99 ± 3.5% of NDN and 65.56 ± 6.71% of LDN expressed CXCR2 in a 4T1 tumor model, only 1.80 ± 1.21% of TANs showed such expression." (PMID 34680231, 2021). "On the other hand, hindering CXCR-2 suppressed angiogenesis, tumour growth, and metastasis and boosted chemotherapeutic response." (PMID 34336101, 2021). "The observed anti-tumor effect was indicated also by a decrease in tumor weight upon anti-CXCR2 therapy." (PMID 33578808, 2021). "In the model of inflammation‐associated CRC, established by dextran sodium sulfate (DSS)–azoxymethane (AOM), CXCR2 knockout contributed to decremental tumor number, and MDSC‐derived CXCR2 was a critical potential mechanism." (PMID 34525267, 2021). "Inhibition of CXCR2 signaling reduces tumor metastasis, enhances sensitivity to anti-PD1 immunotherapy, and prolongs survival in mice." (PMID 35011369, 2021). "In vitro polarization of blood-derived primary human neutrophils under a tumor-mimicking environment resulted in obtaining cells with high surface expression of C-X-C motif chemokine receptor 2 (CXCR2) and secretion of high IL-8 amounts, typical for N2 TANs." (PMID 33917620, 2021). "Primary NK cells from blood and tumor biopsies from patients with renal cell carcinoma engineered ex vivo to express CXCR2, showed enhanced migratory capabilities in vitro." (PMID 34944914, 2021).
tumor (continued). "In this respect, anti-CXCR2 and anti-PD-1 combination therapy reportedly reduces tumour growth and improves the survival of mice inoculated with rhabdomyosarcoma compared to either agent alone." (PMID 34944851, 2021). "The C-X-C chemokine receptor 2 (CXCR2) signaling axis plays a key role in the migration of immunosuppressive MDSCs into the tumor microenvironment (TME) and the pre-metastatic niche." (PMID 34944914, 2021). "In various tumor models, the CXCR2 signaling pathway has been observed to recruit PMN-MDSCs to the TME, and drive tumor invasion and metastasis." (PMID 34403220, 2021). "In this regard, tumor-derived CXCL1, a ligand for CXCR2, has been implicated as a mechanism of resistance to CD40 immunotherapy." (PMID 33497362, 2021). "Fifth, targeting the CXCL8-CXCR1/CXCR2 axis by antagonizing CXCR2 promoted tumor progression in vivo by impeding DC activation or recruitment, leading to the opposite effect of antitumor immunity." (PMID 34025668, 2021). "Both obese CXCR2 WT and cKO mice had larger and more abundant adipocytes in the omental tumor tissues compared to those in lean mice." (PMID 34638514, 2021). "Our results support that CXCLs/CXCR2 chemokine autocrine loop contributes to tumor cellular activities, such as proliferation, apoptosis, senescence and EMT." (PMID 33814009, 2021). "Adipocyte-specific CXCR2 cKO mice fed with HFD had lower tumor burdens, inflammatory areas, proliferation markers, and Mφ infiltration compared to HFD-fed WT mice." (PMID 34638514, 2021). "A number of studies have shown that blocking CXCR2 genetically or pharmacologically can inhibit angiogenesis and tumor growth." (PMID 34124076, 2021). "A preclinical study reported a dual targeted strategy, where CCR2 inhibition combined with CXCR2 blockade resulted in notable tumour suppression and improved survival in tumour‐bearing mice." (PMID 34464477, 2021). "Consistently, the MDSCs were decreased but the CD8+ T cells and granzyme B increased in the tumor tissues of mice given CXCR2 antagonist." (PMID 34108444, 2021). "Inhibition of CXCR2 diminished the tumor migration to LECs, while suppression of p-ERK also decreased levels of key EMT regulators underscoring the important role of ERK as a downstream regulator of the CXCR2-CXCL5 mediated signaling." (PMID 34831316, 2021). "In this regard, we recently demonstrated an efficient CXCR2 antagonization with SB225002 (SB) with a significantly reduced tumor volume, decreased vessel density, and reduced TAM infiltration in an in vivo GL261 syngeneic mouse model." (PMID 34681839, 2021). "Targeting the specific chemokine receptor CXCR2 on MDSCs also prevented MDSCs recruitment to tumor tissues, treatment with the CXCR2 inhibitor SX-682 reduced MDSCs migration to TME and improved the efficacy of anti-PD1 therapy." (PMID 34527668, 2021). "The expression of CXCR2 on myeloid cells from tumor bearing objectives is much higher than that of healthy objectives, which causes the migration of myelocytes to the tumor." (PMID 33814009, 2021). "In vivo study showed that tumor-associated neutrophils (TANs) were significantly infiltrate into tumor tissues of mouse model, with up-regulated CXCLs/CXCR2 signaling and suppressive molecules, including Arg-1 and TGF-β." (PMID 33814009, 2021). "To determine the mechanisms leading to the prolonged survival under the anti-CXCR2 therapy, we analyzed tumor infiltrating MSDC, T, and NK cells." (PMID 33578808, 2021). "Overall, obese CXCR2 WT mice were likely prone to drive OC progression through tumor growth, while obese cKO mice favored ascites accumulation, which required further study to identify the molecular mechanisms." (PMID 34638514, 2021). "Neutrophils express CXC receptors CXCR1 and CXCR2 that can respond to the tumor-derived CXC family chemokines." (PMID 34439836, 2021).
tumor (continued). "Because obese CXCR2 WT and cKO mice had greater tumor weights and ascites accumulation, respectively, we evaluated the correlations between the tumor weights, spleen weights, ascites accumulation, and survival between CXCR2 WT and cKO mice." (PMID 34638514, 2021). "As we verified the angiogenic potential of CXCL2 and IL8, implying an involvement of the CXCR2 axis in tumor angiogenesis, we aimed to investigate the effect of CXCR2 antagonist SB225002 on primary human endothelial cells." (PMID 33807899, 2021). "EOC patients whose tumor cells expressed high levels of CXCR2 had lower OS compared with the cases expressing low levels of CXCR2 (n=0.035)." (PMID 34038868, 2021). "The tumor-derived chemokines implicated in TAM recruitment in BCa include CCL2, SDF-1 and the ligands of CXCR2." (PMID 34572939, 2021). "Having demonstrated that anti-CXCR2 therapy reduced primary tumor weight and prolonged mouse survival, we studied the effect of CXCR2 inhibition on the metastatic process in an adjuvant setting." (PMID 33578808, 2021). "Multiple preclinical and clinical studies have also demonstrated potential benefit for use of other agents targeting tumor stroma in combination with immunotherapy, such as those that target CXCR2." (PMID 34771675, 2021). "Further, dual targeting of CCR2+ TAMs and CXCR2+ TANs restored anti‐tumour immunity and improved the chemotherapeutic effect, providing the theoretical basis for targeting both CCR2 and CXCR2 in future clinical trials." (PMID 34464477, 2021). "This chemokine exerts pleiotropic effects through two G-protein-coupled chemokine receptors CXCR1 and CXCR2 in the tumor microenvironment." (PMID 34200145, 2021). "Meanwhile, miR-940 has also been demonstrated to be remarkably downregulated in hepatocarcinoma tissues and suppress tumor cell invasion and migration through regulating chemokine CXCR2." (PMID 34277600, 2021). "Targeting the CXCL8-CXCR1/CXCR2 axis by antagonizing CXCR2 promotes tumor progression in vivo by impeding DC activation or recruitment, leading to the opposite effect of antitumor immunity." (PMID 34025668, 2021). "We report that high levels of CXCR2 and CD11b were correlated to higher levels of PD-L1 expression on both tumor and stromal cells as well PD-1 by stromal cells." (PMID 34066060, 2021). "In this study, we investigated how adipocyte-specific CXCR2 cKO affects the peritoneal tumor microenvironment of OC in an HFD-induced obese mouse model." (PMID 34638514, 2021). "Tumor-released oxysterols can also act in an LXR-independent, (C-X-C motif) chemokine receptor 2 (CXCR2) dependent way to recruit neutrophils within the tumor microenvironment where they act to suppress tumor-specific T-cells and promote neo-angiogenesis." (PMID 33252713, 2021). "IL8, CXCL2, CXCR1 and CXCR2 are expressed by various GBM tumor cell lines as well as by tumor cells and endothelial cells in GBM patients." (PMID 34203660, 2021). "CXCR2 inhibition prevented neutrophil accumulation in the pancreatic tumors and led to a T cell-dependent suppression of tumor growth." (PMID 34572138, 2021). "In a spontaneous melanoma mouse model, C-X-C motif chemokine ligand 5 (CXCL5) induces recruitment of CXCR2+ MDSCs to the primary tumor." (PMID 34359674, 2021). "Serum CXCL8 and CXCR2 concentrations were significantly higher in GC patients than in healthy controls, similar to the well-established tumor marker (CA19-9) and marker of inflammation (CRP)." (PMID 34680333, 2021). "The authors further highlighted the therapeutic potential for modulating TAMs in the TME by combining treatment with a Cxcr2 inhibitor with infusions of Cxcr2-KO activated monocytes, which further increased the efficiency of tumor inhibition." (PMID 34502458, 2021). "Our novel therapeutic approach combining TMZ with CXCR2 antagonization in vivo was well-tolerated and led to decreased tumor volumes despite the short treatment period of only seven days." (PMID 34681839, 2021).
tumor (continued). "SB225002, a selective inhibitor of CXCR2 showed promising therapeutic effect, and significantly reduced infiltration of neutrophils and enhanced anti-tumor T cell activity via promoting CD8+ T cell activation." (PMID 33814009, 2021). "C-X-C motif chemokine receptor 2 (CXCR2), a member of the G-protein-coupled cell surface chemokine receptor family, is commonly found on leukocytes, endothelial cells and tumor cells." (PMID 34124076, 2021). "Tumor-derived oxysterols recruit pro-tumor Ns through a CXCR2-dependent pathway and promote neoangiogenesis and immunosuppression." (PMID 34742349, 2021). "These chemokines signal though CXCR2 on cancer cells to transform into tumor-initiating cells, thus promoting aggression and treatment resistance." (PMID 35011369, 2021). "Given the role that CXCR2 plays in recruiting MDSCs to the tumor microenvironment, CXCR2 inhibition is a promising strategy to relieve MDSC-mediated immunosuppression and improve the effectiveness of existing immunotherapies." (PMID 34944914, 2021). "Another study found that inhibition of CXCR2 reversed tumor progression promoted by type I collagen deletion in a PDAC mouse model." (PMID 34336821, 2021). "In a model of prostate cancer, an anti-CXCR2 blocking antibody induced the reeducation of TAMs, resulting in a decrease in tumor volume." (PMID 34572939, 2021). "On the other hand, polymorphonuclear-MDSCs express CXCR2 and can be recruited into tumor tissues by CXC chemokines such as CXCL8." (PMID 34885241, 2021). "Based on qRT-PCR analysis, upregulation of Cxcr2 and Cxcl2 were detected in untreated tumor tissue compared to contralateral non-tumor tissue." (PMID 34681839, 2021). "Blocking CXCR1 and CXCR2 with small molecule inhibitor SX-682 significantly abrogated CXCR2+PMN-MDSC tumor accumulation and enhanced the efficacy of both the PD-axis immune checkpoint blockade and adoptive cell transfer of engineered T cells." (PMID 35011369, 2021). "As TAM infiltration affected primary tumor progression in our study, and CXCR2 antagonization has been shown to reduce TAM accumulation, a combination strategy utilizing a CXCR2 antagonist and TMZ seemed appealing." (PMID 34681839, 2021). "Among them, reparixin, SX-682, and AZD5069 are three on course CXCR2 inhibitors undergoing clinical trials of ICI-combined therapies in tumor administration." (PMID 34689842, 2021). "Tumor-bearing mice showed better outcomes with delayed tumor growth and prolonged overall survival when blocking the oxysterol-CXCR2 axis and impairing neutrophil migration." (PMID 34742349, 2021). "An intriguing report showed that obesity led to the CXCR2-mediated accumulation of FasL+ granulocytic MDSCs, resulting in increased apoptosis of tumor-infiltrating CD8+ T cells and immunotherapy resistance." (PMID 34063828, 2021). "Second, the combi-therapy with TMZ and CXCR2-antagonization was evaluated in a syngeneic mouse tumor model with in-depth immunohistological investigations and subsequent gene expression analyses." (PMID 34681839, 2021). "CXCR2 WT mice had a higher correlation between the tumor and spleen weights (R2 = 0.47) than between the tumor weights and ascites (R2 = 0.06)." (PMID 34638514, 2021). "Our results suggest that EOC cells can potentially secret CXCL2 and CXCL8 to TME that act autocrinally on tumor cells CXCR2, conferring the poor prognosis of the disease that is inferred by low patients’ OS." (PMID 34038868, 2021). "In humans and mice, CXCR2 is expressed by tumor cells, neutrophils, mast cells, monocytes, macrophages, endothelial cells, muscle cells, and epithelial cells." (PMID 34944914, 2021). "When studied in mouse models, CXCR2 knock out led to a reduction of neutrophils and a proportional suppression of tumor growth." (PMID 34771675, 2021).
tumor (continued). "While in the tumor microenvironment, the high affinity of IL-8 to CXCR1 and CXCR2, the activation of which has been demonstrated to play an important role in tumor progression, would contribute a great deal to the malignant process." (PMID 34497832, 2021). "KrasG12D-induced cytokines and CXCR2-related chemokines have been reported to facilitate myeloid cell infiltration and tumor progression." (PMID 34237033, 2021). "T cells genetically modified to express CXCR2 were shown to migrate toward a host of tumor cells expressing CXCL1." (PMID 35008832, 2021). "In summary, it can be said that CXCR2 was significantly upregulated in the GL261 GBM tumor model compared to healthy tissue, with a decrease after each therapy." (PMID 34681839, 2021). "KRAS-mediated repression of interferon regulatory factor 2 (IRF) results in the high expression of the chemokine C-X-C motif ligand 3 (CXCL3), which induces MDSCs that express C-X-C motif chemokine receptor 2 (CXCR2) as the receptor of CXCL3 in tumor tissues." (PMID 34359568, 2021). "CXCL1, an important ligand of CXCR2, which promotes cancer chemoresistance, progression and metastasis 54, recruits MDSCs to tumor site to induce immune suppression." (PMID 33897880, 2021). "The CXCR2 antagonist SB225002 has shown inhibition in tumor growth, and led to reduced number of TAMs as well as tumor vessels." (PMID 34422657, 2021). "We find that Cxcr2 ablation leads to an increase of both primary tumor growth and the development of lung metastasis." (PMID 34070438, 2021). "Based on the IHC scores of each tumor tissue, CXCR2 expression in tumor stoma was higher than that on tumor cells." (PMID 33814009, 2021). "As previously reported, tumor-associated macrophages in primary CRC tumors recruit MDSCs into the liver and generate pre-metastatic sites through the CXCL1/CXCR2 pathway." (PMID 33833986, 2021). "Altogether, our study indicates a central effect of CXCR2 in preventing tumor progression, due to acquisition of cisplatin chemoresistant phenotype by tumor cells, and patients’ high lethality rate." (PMID 34038868, 2021). "Tumour cells express ligands for the MDSC chemokine receptor CXCR2 which, upon binding, encourages MDSC infiltration into the TME." (PMID 34944851, 2021). "CT26 model also provided CXCR2 dependent mediated the trafficking and function of tumor-infiltrating immune cells in the TME." (PMID 34025668, 2021). "Focusing on the driving forces behind NDN and LDN recruitment into the tumor, the surface expression of CXCR2 and CXCR4 receptors was checked in NDN, LDN, and TANs." (PMID 34680231, 2021). "Hypoxia-induced CXCR-2 expression on tumour cells is time-dependent, contributing to the survival of tumour cells through NF-κB and HIF-1 signalling." (PMID 34336101, 2021). "Further, upregulation of the CXCR2-axis in PDAC is associated with tumor-supporting inflammation, immunosuppression, angiogenesis and tumor growth." (PMID 34359823, 2021). "Circulating and tumor-derived oxysterols have been also described to recruit pro-tumor neutrophils and to increase neo-angiogenesis and immunosuppression in a CXCR2-dependent and LXR-independent manner." (PMID 33224146, 2020). "In the present paper we demonstrated that serum CXCR4 and CXCR2 were significantly elevated in PC patients compared to healthy controls, similarly to the classical tumor marker and CRP." (PMID 32867211, 2020). "CXCR2 was highly and equivalently expressed on tumor-infiltrating G-MDSCs from both lean and obese animals." (PMID 33123173, 2020). "It was illustrated that 22(R)-HC is a naturally-occurring chemotactic ligand of CXCR2 and facilitated tumour growth by promoting neoangiogenesis or immunosuppression." (PMID 32998240, 2020). "In primary tumours, we observed a significant increase in the number of CXCR4+, but not of CXCR2+ cancer cells while the number of CXCR2+ TICs was also significantly increased in JL tumours." (PMID 32581213, 2020).